SNHG16 (small nucleolar RNA host gene 16)
Diseases named in the same sentence as SNHG16 in open-access papers (continued):
Sharing a sentence is not in itself a finding about the gene and the disease.
cancer (65 papers, 2016 to 2025). A tumor composed of atypical neoplastic, often pleomorphic cells that invade other tissues. "SNHG16, as a potential oncogenic factor in many cancers, was usually associated with the modulation of miRNA to influence the occurrence and development of tumor cells." (PMID 39279987, 2022). "Of these, SNHG16 is best categorized and is often found overexpressed in cancers where it is associated with poor prognosis." (PMID 34556693, 2021). "The current review briefly summarizes recently reported findings about SNHG16 and discuss its expression, roles, mechanisms, and diagnostic and prognostic values in human cancers." (PMID 32944244, 2020). "Although SNHG16 plays important roles in different cancers, its functional role and underlying molecular mechanism in MM tumorigenesis are still largely unclear." (PMID 32025219, 2020). "The lncRNA SNHG16 has been implicated for its important roles in regulating cancer progression, and various molecular mechanisms for SNHG16 were also proposed." (PMID 31441592, 2019). "SNHG16 has been implicated as an oncogene in various cancers, including BC." (PMID 39448672, 2024). "In addition, SNHG16 has been described as a promising diagnostic and prognostic biomarker in cancer patients." (PMID 32944244, 2020). "SNHG16 might also represent a promising noninvasive diagnostic marker in cancer in combination with other specific biomarkers, because it is found in body fluids, including plasma, serum, and serum exosomes." (PMID 32944244, 2020). "SNHG16 expression is tightly associated with tumor size in several human cancer types." (PMID 32944244, 2020). "In relation to clinical practice, SNHG16 dysregulation shows associations with clinical phenotypes as well as patient survival in many cancers, suggesting that SNHG16 might be a prognostic marker." (PMID 32944244, 2020). "Small nucleolar RNA host gene 16 (SNHG16) belongs to long noncoding RNA (lncRNA) family, and has been proved to be associated with the tumorigenesis of many cancer types, moreover, lncRNAs act frequently as a tumor suppressor or promoter of the activation of oncogene." (PMID 32324343, 2020). "In this meta-analysis, we report, for the first time, the comprehensive role of SNHG16 expression in human pan-cancers, which may provide promising targets for the development of novel diagnostic and therapeutic strategies against cancers." (PMID 31632195, 2019). "In conclusion, our results infer that high SNHG16 expression was strongly associated with unfavorable survival outcome of several cancers and therefore might serve as a novel prognostic biomarker and potential therapeutic target in cancer patients." (PMID 31632195, 2019). "Many studies have revealed that SNHG16 plays a vital role as an oncogene in numerous cancers through various of pathways." (PMID 36949429, 2023). "As an activator of the Hedgehog pathway via miR-802/PTCH1, SNHG16 is also upregulated in cancer stem cells (CSCs)." (PMID 37600653, 2023). "Among the 22 SNHG families, SNHG5, SNHG7, SNHG12, and SNHG16 are all known to promote cancer progression." (PMID 37189636, 2023). "Small nucleolar RNA host gene 16 (SNHG16) is located on 17q25.1 and was recently identified as a cancer-associated lncRNA." (PMID 35965433, 2022). "Among the 11 autophagy-related lncRNAs, 8 lncRNAs were already verified to be associated with cancer development: LINC01063, CD27-AS1, LINC00957, EIF3J-DT, LINC02474, SNHG16, LINC02381, and LINC01011." (PMID 36035142, 2022). "Subsequent studies have revealed that SNHG16 competitively binds with miR-4518, miR-140-5p, miR-4500 and miR-302a-3p in various cancer types." (PMID 36221055, 2022). "The long non-coding (lnc) RNA activated by small nucleolar RNA host gene 16 (SNHG16), which has been reported to play a vital role in a number of different types of cancer, is a novel lncRNA." (PMID 33823834, 2021).
cancer (continued). "Recent studies have shown that SNHG16 is upregulated in a variety of human cancers and significantly correlated with advanced pathological stage, lymph node metastasis, and poor prognosis in cancer patients." (PMID 34760707, 2021). "Not only in cancer, recent evidence suggest that SNHG16 also has a significant impact on regulating the inflammatory response." (PMID 32677912, 2020). "In recent years, SNHG16 has been highlighted with its important functions in mediating these oncogenes and tumor suppressors and generally regulating these cancer characteristics." (PMID 32944244, 2020). "Some studies have revealed that upregulated SNHG16 expression predicted poor prognosis for some cancers." (PMID 32677912, 2020). "SNHG16 has been reported to function as a molecular sponge for multiple miRNAs in cancers, such as miR-98-5p, miR-135a, and miR-373." (PMID 32025219, 2020). "There are growing evidence of SNHG16’s involvement in characteristics of cancer, including proliferation, apoptosis, together with its involvement in chemoresistance." (PMID 32944244, 2020). "Taken together, data from previous reports and the The Cancer Genome Atlas (TCGA) database indicate the upregulation of and an oncogenic role for SNHG16 in various cancers, although discrepant findings require clarification." (PMID 32944244, 2020). "The most common mechanistic actions of SNHG16 in regulating cancer progression are the ceRNA function to repress its downstream targeted miRNAs such as miR‐216, miR‐98, miR‐340 and miR‐302a‐3p." (PMID 31441592, 2019). "LncRNA small nucleolar RNA host gene 16 (SNHG16) has been recognized as a tumour‐promoting factor in various types of cancer." (PMID 31483572, 2019). "SNHG16 is a crucial lncRNA that drives the malignant development of various cancers." (PMID 37846311, 2023). "In recent years, the pivotal role of SNHG16 in cancer has been gradually uncovered." (PMID 37846311, 2023). "Currently, SNHG16 is considered as an oncogene in many cancers." (PMID 37280692, 2023). "Some studies have shown that SNHG16 contributes to chemotherapy resistance in cancer." (PMID 36816365, 2023). "Small nucleolar RNA host gene 16 (SNHG16) is a proto-oncogene common to various types of cancer." (PMID 33981224, 2021). "SNHG16 is reportedly increased and acts as a tumor promoting role in various cancers." (PMID 32025219, 2020). "However, SNHG16 is found in multiple cancer types and less likely to help distinguish the specific origins of tumors." (PMID 32944244, 2020). "Given the suppressive role of miR-342-3p in cancer, we aimed to determine whether SNHG16 acts as an miR-342-3p sponge to regulate the proliferation and apoptosis of MM cells." (PMID 32025219, 2020). "Since then, SNHG16 upregulation has been demonstrated in major human cancers." (PMID 32944244, 2020). "Similarly, SNHG16 is also a member of the lncRNA molecule, and several studies have indicated that it can promote the progression of malignant tumors." (PMID 32323054, 2020). "Our experimental data also suggested that the lnc-SNHG16/miR‐128/WNT/β-catenin axis may be a promising therapeutic target for CC or other cancers." (PMID 32127947, 2020). "These authors speculated that the site and microenvironment of a given malignancy might provide explanations regarding differences in SNHG16 expression compared with other human cancers." (PMID 32944244, 2020). "Clearly SNHG16 could regulate the growth and proliferation of various cell lines, and thus regulate the growth of cancers in xenograft models." (PMID 32944244, 2020). "Subsequent studies showed that SNHG16 was deregulated and function in several cancers." (PMID 32944244, 2020). "Taken together, SNHG16 could serve as a functional regulator and potential biomarker of poor prognosis in pan-cancer patients." (PMID 31632195, 2019). "Several studies have revealed the mechanism involved in the deregulation of SNHG16 in human cancer." (PMID 31483572, 2019).
cancer (continued). "However, whether USP21/YY1/SNHG16 plays a cancer-promoting role in a feedback loop needs to be further studied." (PMID 31956270, 2020). "Moreover, SNHG16 may be also engaged in the pathogenesis and progression of cancers, including proliferation, migration and invasion." (PMID 31632195, 2019). "Interestingly, SNHG16, a lncRNA with upregulated expression in invasive, sphere-forming and TX-resistant HEC-50 cells, has been implicated in tumor promotion in a number of cancers other than EC." (PMID 31287002, 2019). "As a cancer-promoting factor, HMGB1 is also regulated by lncRNA small nucleolar RNA host gene 16 (SNHG16)/miR-218-5p 69 and lncRNA zinc finger E-box binding homeobox 2 antisense RNA 1 (ZEB2-AS1)/miR-204 70 axis in PC." (PMID 38725864, 2024). "Here we establish broad relevance of 2 snoRNA host genes, SNHG16 and SNHG6, to a variety of cancers and neuropsychiatric disorders specifically through their relationship with vitamins, well supported by multiple studies." (PMID 38475720, 2024). "Previous studies have indicated that SNHG16 promotes tumor development through EMT and predicts poor survival outcomes in several cancers (Cao, Xu, and Yue, 2018; Bu, Guo, Xu, Luo, and Liu, 2021)." (PMID 35359436, 2022). "These authors also observed positive correlations between the expression level of the small nucleolar RNA host gene 16 (SNHG16) and LINC00511 genes and nuclear grade, tubule formation, and family history of cancer." (PMID 35328609, 2022). "Small nucleolar RNA host gene 16 (SNHG16) is located in chromosome 17q25.1, has been shown to be involved in the mechanisms of various cancers." (PMID 37303939, 2021). "Thus, SNHG16 may represent a potential therapeutic candidate in a variety of cancer types." (PMID 32944244, 2020). "To examine the potential role of SNHG16 in tumorigenicity, we observed the growth process of a CRC cancer-cell xenograft." (PMID 30962265, 2019). "Through utilizing starBase (selection condition: CLIP-Data > = 5; pan-Cancer > = 4), three lncRNAs (FGA5-AS1, NEAT1 and SNHG16) that could bind to miR-124-3p were predicted." (PMID 35761386, 2022). "SNHG16 negatively modulates miR-128-3p, preventing its interaction with its targeted gene HOXA7, a sequence-specific transcription factor involved in many human cancers." (PMID 33921816, 2021). "In recent years, a numbers of lncRNAs [LncRNA uc.372, SNHG16, SNHG1, or MALAT1] were observed to negatively regulate miR-16 family member expression and played a role in pathogenesis of cancers." (PMID 31316397, 2019). "SNHG16 has been identified as an oncogene in many cancers; however, its function in ESCC is not completely investigated." (PMID 29416674, 2018). "However, it is unclear why the level of SNHG16 is lower in exosomes of sera from cancer patients versus non-cancer individuals." (PMID 34571795, 2021). "Overexpression of SNHG16 could lead to changes in cancer cell proliferation, apoptosis, migration, invasion, epithelial-mesenchymal transition (EMT) and chemoresistance in a majority of cancers." (PMID 31632195, 2019). "Besides, SNHG16 could interact with a variety of signaling pathways including Wnt/β-catenin and PI3 K/Akt in the pathogenesis of cancers." (PMID 31632195, 2019). "Furthermore, SNHG16 might have a transcriptional role through epigenetic modification: for example, in CC, SNHG16 can recruit SPI1, a transcription factor for PARP9, leading to the development of cancer." (PMID 33921816, 2021). "Results indicated that these treatments had no any effects on serum levels of MEG3, SNHG16 and MALAT1, which provides a base for cancer diagnosis as the useful and stable biomarkers." (PMID 27793008, 2016).
tumor (48 papers, 2017 to 2025). "The exosome lncRNA Small nucleolar RNA host gene 16 (SNHG16)/miR-4500/N-acetylgalactosamine-transferase 1 (GALNT1) axis has been linked to tumor angiogenesis." (PMID 37007117, 2023). "The expression of SNHG16, an independent prognostic predictor, is associated with tumor size and sorafenib resistance of LIHC patients." (PMID 36906605, 2023). "The upregulation of SNHG16 was confirmed to be associated with tumour severity and detrimental to clinical outcomes." (PMID 33968736, 2021). "The lncRNA small nuclear RNA host gene 16 (SNHG16), found on chromosome 17q25.1, represents a novel tumor-associated lncRNA." (PMID 32944244, 2020). "Assay testing has shown that SNHG16, which has been shown to interact with the NF‐κB pathway, was significantly up-regulated both in the tumor samples and peritumoral cirrhotic parenchyma compared to cirrhotic CVH parenchyma samples (15.7 and 19.4 fold)." (PMID 39397388, 2025). "For example, tumor-killing immune cells in the high expression group of SNHG16, SNHG6, SNHG11, FAM222A-AS1, RHPN1-AS1, SNHG1, and SNHG7 were significantly lower than those in the low." (PMID 35646635, 2022). "Previous studies have shown that LINC00426 and SNHG16 can promote tumor development and participate in the regulation of TIME." (PMID 35571063, 2022). "SNHG16 knockdown inhibited the colony formation, proliferation, migration, and invasion of CRC cells, and YAP1 overexpression rescued the effect of SNHG16 knockdown on tumor progression." (PMID 36147462, 2022). "Numerous studies have confirmed that SNHG16 acts as a tumour suppressor during CRC development by regulating tumour cell invasiveness and metastasis in vivo and in vitro." (PMID 34490250, 2021). "In recent years, many studies have demonstrated that abnormal expression of SNHG16 does not only correspond to one tumor, but also can been detected different tumor tissues from various systems." (PMID 32677912, 2020). "And SNHG16 participates in regulating the biological functions of tumor cells through complex regulatory mechanisms, such as cell proliferation, migration, invasion and apoptosis." (PMID 32677912, 2020). "lnc-SNHG16 is significantly positively associated with TNM stage, tumor size, distant metastasis and the prognosis of survival in patients with CC." (PMID 32127947, 2020). "In HCC, SNHG16 is significantly upregulated in both tumor tissues and cell lines." (PMID 41301542, 2025). "In addition, SNHG16 is regulated by the Wnt pathway and is involved in lipid metabolism in clinical tumours." (PMID 36949429, 2023). "The tumor regulatory role of SNHG16 was also evident from the in vivo mice tumorigenesis study." (PMID 35646120, 2022). "To investigate whether the function of SNHG16 in tumor progression is dependent on YAP1, we performed a rescue experiment." (PMID 36147462, 2022). "Altogether, SNHG16 exerted a tumour‐promoting role in DLBCL." (PMID 31483572, 2019). "In summary, these results provide new insights into the tumour‐promoting role of the SNHG16/miR‐497‐5p/PIM1 axis in DLBCL progression, which may improve our understanding of the pathogenesis of DLBCL and provide potential therapeutic targets." (PMID 31483572, 2019). "The present study indicated the functional role of SNHG16 in OS cells, in that SNHG16 knockdown could suppress cell proliferation, migration, invasion and promoted apoptosis in OS cells in vitro, as well as inhibit tumor growth in vivo; however, the regulation of SNHG16 expression remains unclear." (PMID 33823834, 2021). "For instance, the expression small nucleolar RNA host gene 16 (SNHG16) has been proved to be increased in tumor tissues and cell lines of HCC, and inhibition the expression of SNHG16 could repress the sorafenib resistance, proliferation, migration and invasion of HCC cell lines." (PMID 32595415, 2020).
tumor (continued). "Furthermore, miR‐23b‐3p in sorafenib‐treated Hep3B/So cells enlarged the tumor size more than Hep3B/So + So, Hep3B/So + si‐SNHG16 + So and Hep3B/So + si‐SNHG16 + inhibitor+So groups, suggesting that the inhibition of miR‐23b‐3p was able to significantly increase the tumor size." (PMID 32324343, 2020). "Notably, high SNHG16 expression was significantly correlated with larger tumor size (OR = 6.36, 95% CI 2.43–16.60, P = 0.0002), poor clinical stage (OR = 2.91, 95% CI 1.60–5.28, P = 0.005), LNM (OR = 4.42, 95% CI 2.66–7.35, P = 0.0001) and DM (OR = 3.86, 95% CI 1.92–7.77, P = 0.002)." (PMID 31632195, 2019). "Further, in vivo study also revealed that overexpression of SNHG16 could promote tumor growth." (PMID 30962265, 2019). "Similar to SNHG16, SNHG6 regulates gene expression transcriptionally by recruiting EZH2 to promoter regions of different tumor suppressor genes, such as P27 and P21, and represses their expression through methylation of their promoters." (PMID 35740344, 2022). "SNHG16 expression was significantly upregulated in CRC tissues in the TCGA database and our cohort, and its high expression correlated the advanced tumor-node-metastasis (TNM) stage." (PMID 36147462, 2022). "Colony formation, CCK8, Transwell, and wound healing assays revealed that YAP1 overexpression significantly promoted tumor progression, whereas the promotive effect on HCT116 was impaired by simultaneous knockdown of SNHG16." (PMID 36147462, 2022). "SNHG16 was expressed to a greater extent in MIBC than in NMIBC, suggesting that it stimulates tumour progression." (PMID 33968736, 2021). "Although we elucidated the roles of sIRlncRs on forecasting prognosis and verified the expression levels of SNHG16 and ADAMTS9-AS in tumor tissues, some limitations remain to be further discussed." (PMID 32716909, 2020). "Taken together, we reported that lnc-SNHG16/miR-128 axis modulated the proliferation, migration and invasion and EMT process in vitro and tumor growth in vivo through the WNT/β-catenin pathway." (PMID 32127947, 2020). "Expression of the seven lncRNAs UCA1, MALAT1, H19, GAS5, TUG1, ncRAN (SNHG16) and linc-UBC1 (BLACAT) was measured by RT-qPCR in UC tissue set 1 consisting of 106 tumor tissues and 10 benign tissues obtained from radical cystectomies." (PMID 28430799, 2017). "The low expression group of SNHG16, SNHG6, SNHG11, FAM222A-AS1, RHPN1-AS1, SNHG1, and SNHG7 was accompanied by more immune cell infiltration, further supporting that PANoptosis plays a crucial role in the tumor immune microenvironment." (PMID 35646635, 2022). "In summary, the present study demonstrates the tumour‐suppressive role of miR‐605‐3p in HCC metastasis for the first time and indicates the importance of the interactions between SNHG16, miR‐605‐3p, TRAF6 and the NF‐κB pathway in the regulation of HCC cell malignancy." (PMID 32436333, 2020). "In addition, the role of SNHG16, another lncRNA, in inducing migration and autophagy through upregulating ATG5 was reviewed, and this molecule may also be affecting tumour growth, proliferation and migration steps (steps 1–2 and 4)." (PMID 36983973, 2023). "Therefore, SNHG16 and YAP1 form a positive feedback loop to regulate tumor progression." (PMID 36147462, 2022).
gynecological tumors (1 paper, 2021). "SNHG16 also plays an important role among gynecological tumors." (PMID 37303939, 2021).
SNHG16 also shares sentences with these, for which no sentence is quoted: non-small cell lung carcinoma (4 papers); esophageal squamous cell carcinoma (3); lymph node metastasis (3); clear cell renal cell carcinoma (2); colorectal adenocarcinoma (2); esophageal cancer (2); gastric adenocarcinoma (2); lung adenocarcinoma (2); acute myeloid leukemia (1); adenoma (1); aggressive (1); bladder urothelial carcinoma (1); breast invasion carcinoma (1); colon adenocarcinoma (1); colorectal (1); digestive system cancer (1); gastric tumors (1); hemorrhage (1); inflammatory bowel disease (1); leukemia (1); lung injury (1); lung squamous cell carcinoma (1); lymphoma (1); neurodegenerative disease (1); oral squamous cell carcinoma (1); prostate carcinoma (1); rectum adenocarcinoma (1); renal cell carcinoma (1); retinopathy (1); retinopathy of prematurity (1).
A further 2 diseases each share a sentence with SNHG16 in 1 paper.